IFI27 (interferon alpha inducible protein 27)
Diseases named in the same sentence as IFI27 in open-access papers (continued):
Sharing a sentence is not in itself a finding about the gene and the disease.
lung fibrosis (1 paper, 2022). "EGFR+ SSc fibroblasts also expressed higher levels of interferon inducible genes (IFI27, BST2), which have been shown to correlate with SSc disease severity, and IL6, a profibrotic cytokine whose inhibition slows SSc-associated lung fibrosis." (PMID 36490328, 2022).
lupus nephritis (1 paper, 2024). Glomerulonephritis in the context of systemic lupus erythematosus. "There is evidence that IFI27 expression clustered with the fraction of SLE cases having African ancestry or lupus nephritis, which also has growth inhibitory and anti-viral functions, including the ability to sensitize cells to apoptosis that is the same as other common ISGs." (PMID 39080788, 2024).
lymph node metastases (1 paper, 2025). "To investigate the potential role of CD4+ Tregs in lymph node metastases, we identified the upregulated genes in CD4+ Tregs from metastatic lymph nodes, including IFI27, IL2RA and IL2RB." (PMID 39741182, 2025).
mastitis (1 paper, 2024). Inflammation of breast tissue during lactation or postpartum due to an obstructed duct or infection. "Hence, we speculated that the IFI27 gene might have an effect on intracellular NEFA and TGs content when Chinese Holstein cows suffer from mastitis." (PMID 39595334, 2024).
metastatic prostate carcinoma (1 paper, 2013). A carcinoma that arises from the prostate gland and has spread to other anatomic sites. "In our previous gene expression study, the interferon alpha-inducible protein 27 (IFI27) is the most up-regulated gene whole blood RNA of men with non-metastatic prostate cancer receiving localized EBRT." (PMID 23959120, 2013). "The interferon alpha-inducible protein 27 (IFI27) was the most up-regulated gene based on our previous microarray data in fatigued men with non-metastatic prostate cancer receiving localized external beam radiation therapy (EBRT)." (PMID 23959120, 2013).
multiple sclerosis (1 paper, 2016). A progressive autoimmune disorder affecting the central nervous system resulting in demyelination. "Medical records revealed that patient DIGI1 patient had undergone IFN-β1b (Betaferon®) treatment for therapy of multiple sclerosis prior to blood collection; this treatment may induce IFI27 expression." (PMID 27100186, 2016).
myelofibrosis (1 paper, 2019). A partial or complete replacement of the bone marrow stroma by fibrous tissue. "For example, the expression of the gene IFI27 is upregulated more than 1,100‐fold in D and this may be indicative of a process of myelofibrosis or fibrotic scarring of the bone marrow." (PMID 31134759, 2019). "Its upregulation in β‐thalassemia may be indicative of myelofibrosis, or an inflammation and scarring of the bone marrow, seen also in Philadelphia‐negative chronic myeloproliferative neoplasms where there is an exceedingly high level of expression of IFI27 in whole blood." (PMID 31134759, 2019).
myxoma (1 paper, 2024). A benign soft tissue neoplasm characterized by the presence of spindle and stellate cells, lobulated growth pattern, and myxoid stroma formation. "Macrophages in myxoma were associated with the upregulation of NFKB1, PDGFC, and IL1B, as well as the downregulation of ATP5PB, HSPB1, and IFI27." (PMID 39090109, 2024).
Oral leukoplakia (1 paper, 2021). A thickened white patch on the oral mucosa that cannot be rubbed off. "Although previous studies have explored the molecular mechanism by which diseases associated with IFI27 include Hepatitis C Virus and Oral Leukoplakia." (PMID 33468161, 2021).
parasitemia (1 paper, 2021). "More specifically, interferon-alpha inducible protein 27 (IFI27) levels have been found to correlate with clinical parameters and thus could represent a potential indicator of parasitemia, along with hemoglobin and lactate levels." (PMID 33806981, 2021).
psoriasis vulgaris (1 paper, 2022). Plaque psoriasis is the most common presentation of psoriasis. "In summary, we demonstrated that the presence of IL36G may mediate the keratinocyte expression of AVPs such as MX1, ISG15, IFI27, and IFI44L in psoriasis vulgaris." (PMID 36172384, 2022).
respiratory syncytial virus infection (1 paper, 2025). "IFI27 has been mentioned as a potential diagnostic marker for respiratory syncytial virus infection in preterm infants; however, its predictive efficacy was not evaluated in the study." (PMID 40843077, 2025).
RSV bronchiolitis (1 paper, 2015). "IFI27 up-regulation was observed in hospitalized infants with RSV bronchiolitis, yet it was not seen in the three healthy adults infected with RSV in our study." (PMID 26070066, 2015).
sarcoidosis (1 paper, 2020). Sarcoidosis is a multisystemic disorder of unknown cause characterized by the formation of immune granulomas in involved organs. "Only IFI27 was significantly upregulated in TB (p 0.0000678 FC > 6) but didn’t achieve significance in Sarcoidosis." (PMID 33276795, 2020).
schizophrenia (1 paper, 2022). A major psychotic disorder characterized by abnormalities in the perception or expression of reality. "Interestingly, there is some evidence that IFI27 is differentially expressed in transgenic mice that exhibit schizophrenia-like behaviours." (PMID 35716830, 2022).
serous ovarian cancer (1 paper, 2010). "That is, one group including: SSBP1, IFI6 DDT, IFI27, C11orf92, NFKBIA, TNXB, NEAT1 and TFG, was up-regulated in most patients with stage III serous ovarian cancer." (PMID 20969748, 2010).
steatosis (1 paper, 2024). Increased lipid within the cytoplasm of cells. "In GSE89632 dataset, with the highest number of participants (n = 63), IFI27 was significantly upregulated by 7% and 5.4% in steatosis and NASH, respectively, as compared with healthy individuals (normal) (adj." (PMID 39562169, 2024).
synovitis (1 paper, 2025). Inflammation of a synovial membrane. "Studies have shown that high expression of IFI27 is related to synovitis in SLE patients." (PMID 40297850, 2025).
infection (77 papers, 2008 to 2025). The state of being infected such as from the introduction of a foreign agent such as serum, vaccine, antigenic substance or organism. "Blood IFI27 expression is superior to MX1 expression for diagnostic accuracy across the time course of symptomatic infection and thereby, offers higher diagnostic yield for respiratory virus infections that incur a delay between transmission and testing." (PMID 39616162, 2024). "We further examine the role of IFI27 expression for risk stratification in infections caused by other respiratory viruses, namely influenza virus, another virus of pandemic potential." (PMID 36685600, 2022). "This included IFITM1 and IFITM2, which are known to inhibit the infection and replication of respiratory syncytial virus, IFI27, a known biomarker for RSV29, and IRF7, a gene associated with suppression of innate immunity response." (PMID 31554845, 2019). "Finally, the delay between transmission and testing in naturally acquired infection means that overall IFI27 transcripts achieve greater diagnostic accuracy than MX1 transcripts as a diagnostic triage test for respiratory virus infection." (PMID 39616162, 2024). "Among the infection-specific ISGs upregulated during ΔHA-Cre infection are genes associated with apoptosis (Ripk2, Casp1, Ifi27, Pmaip1) and E3 ubiquitin ligases and proteasome genes, some of which are known to be involved in MHC-I antigen processing (Neurl3, Rnf19b, Psmb9)." (PMID 32790753, 2020). "In every concentration and infection-condition, IFI27 overexpression leads to a lower level of luminescence compared to the empty control." (PMID 40522981, 2025). "At 24 hours post-transfection, cells were either mock or VSV infected, at a MOI of 0.1, and 24 hours after infection, cells were harvested, and protein extracts were used to measure RLuc signal and IFI27-HA expression was confirmed by Western Blot." (PMID 40522981, 2025). "IFI27 is among the most upregulated genes in infection, cancer, inflammation, and autoimmune disorders, and its modulation of immune and metabolic pathways in the tumor microenvironment promotes PDAC progression and is associated with poor prognosis." (PMID 41465457, 2025). "The utilization of single-cell resolved spatial transcriptomics to delineate immune responses during SARS-CoV-2 infection was able to identify M1 macrophages to have elevated expression of IFI27 in areas of infection." (PMID 38377798, 2024). "Among time points in which at least one of these biomarkers was elevated ( > Z2) to signify replicative infection the ratio of MX1:IFI27 levels best correlated with time from virus challenge." (PMID 39616162, 2024). "While the number of significantly upregulated genes decreases to 37, these genes (e.g., ISG15, IFI6, IFI44L, HP, OAS1, IFI44, OASL, and IFI27) likely play a crucial role in the response to the progressing infection." (PMID 39282474, 2024). "Blood MX1 expression is superior to IFI27 expression for diagnosis of early infection, as a correlate of viral load and for discrimination of virus culture positivity." (PMID 39616162, 2024). "When comparing the models that include infection clearance by the different ISGs, we identified that the per-capita clearance rate of infected cells is a median of 2.5 times faster per IFI27 gene expressed than it is per IFI6 gene expressed (bF1/bF3)." (PMID 39575237, 2024). "Particularly on day 13 post-infection, IFI27, among other ISGs, was found to be highly expressed, aligning with the peak antiviral response in the patient." (PMID 39282474, 2024). "Nonetheless, for nose samples which did yield RNA sequencing data, we found clear evidence of MX1 and IFI27 responses in participants who developed a replicative infection." (PMID 39616162, 2024).
infection (continued). "Further evidence for the crucial role of IFI27 is provided in a large-scale nested case-control diagnostic accuracy study where, IFI27 is suggested as a marker for the early detection of SCOV2 infection and for "abortive infection" events." (PMID 38077337, 2023). "Many antiviral ISGs were upregulated in early stages of infection, with IFI27, OTOF, ISG15, MX1 and USP18 the most highly overexpressed." (PMID 37077524, 2023). "High levels of expression of IFI27 have been reported previously, across different stages of infection, and the gene was even put forth as a ‘potential therapeutic target for HIV infection’ based on its downregulation after ART commencement." (PMID 37077524, 2023). "A single interferon-stimulated gene, IFI27, was identified as the best discriminator of PCR-detectable infection—performing better than any previously identified combination of genes/signature of respiratory infection." (PMID 36901802, 2023). "This is supported by the more prolonged induction of IFI27 observed in our abortive cohort than the shorter, but higher IFI27 signal in those with classical infection." (PMID 36901802, 2023). "Both IFI6 and IFI27 transcripts were increased upon infection with P. vivax, however only 23% of the P. vivax positive cells co-expressed the 2 genes." (PMID 35443155, 2022). "Since we wanted to see how the protein level of IFI27 changed after cells were infected with C. parvum, we took 0 h as the infection control." (PMID 35974384, 2022). "In HCV-infected liver biopsies, ARHGEF3 was modestly upregulated 1.5–2-fold during HCV gt1 and gt3 infection; by comparison, IFI27 and RSAD2/VIPERIN were induced >10–100 fold during HCV infection." (PMID 36016278, 2022). "For the gene silencing approach, we utilized siRNA oligonucleotides to specifically reduce expression of IFI6 and IFI27 prior to infection." (PMID 35443155, 2022). "Previous research shows that IFI27 gene expression is elevated in monocytes from HIV-suppressed HCV coinfected compared to HCV mono-infected participants and in vitro infection of monocyte derived macrophages with HIV-1 downregulates IFI27 gene expression." (PMID 34388205, 2021). "The IFNT induced expression of TRIM56, DDX58, and IFIH1 was further enhanced in the cells infected with KY (IFNT vs. IFNT+KY, P < 0.05–0.01) and that of TRIM56 and IFI27 was further increased in the presence of HO infection (IFNT vs. IFNT+HO, P < 0.05)." (PMID 33898551, 2021). "Nevertheless, several downstream genes of the type I IFN signaling pathway were elevated, consistent with reports of other New World arenavirus human infection, including Ifi27, Ifi27l2b, Ifi44, Ifi204, Ifit1, Mx1 and Mx2." (PMID 29724035, 2018). "These include Ifi27, Ifih1, Irf7 and Oas1b which were upregulated at 72 hr and 96 hr post infection except Becn1 that was over-expressed only at 72 hr post infection, and Spn which was over-expressed at all time points." (PMID 18558011, 2008). "The consistent upregulation of IFI27 in Ebola-infected NHPs, as compared to their negative counterparts, underlines its significance in the pathophysiology of the infection." (PMID 39282474, 2024). "This difference was less evident in data from convalescent patients, and consistent with transient cell-type specific opening of the IFI27 locus in established infection, providing a mechanistic basis for the temporal delay and cellular restriction of IFI27 responses compared to MX1." (PMID 39616162, 2024). "We also confirmed that IFI27 was upregulated during primary infection in B-cells." (PMID 38300891, 2024). "Moreover, our study revealed the significant role of genes like IFI6, which, alongside IFI27, showed marked expression level changes in response to the infection." (PMID 39282474, 2024). "Infection of microglia was associated with a sharp increase in CCL2 and CXCL10 chemokine gene expression and the activation of many type I interferon stimulated genes (MX1, ISG15, ISG20, IFI27, IFITM3 and others)." (PMID 38737767, 2024).
infection (continued). "Expression of IFI27 is induced after infection with different viruses." (PMID 37187533, 2023). "Moreover, IFI27 downregulation was involved in the C. parvum burden by regulating cell apoptosis through a TRAIL-dependent pathway during the early phase of infection." (PMID 35974384, 2022). "At 72 hours post-infection IFI27 expression was upregulated in infected nasal epithelial cells." (PMID 36685600, 2022). "The description of host genetic and transcriptional markers in experimental infection is relatively common and has revealed promising candidates such as IFI27, which appears to be an early marker also for other respiratory virus diseases to facilitate early infection recognition." (PMID 35883640, 2022). "Overall, our results indicate that targeting IFI27 might reduce the molecules that mediate immmune infection, suggesting that the potential value of combining blockades of IFI27 and coinhibitory molecules may serve as a new immunotherapy against SLE." (PMID 33468161, 2021). "For example Oas1b, Ifi27, Ifih1 and Irf7 genes were up-regulated at 72 and 96 hr post infection." (PMID 18558011, 2008). "A few genes identified during the IgG peak such as IFI27 (up-regulation), S-formylglutathione hydrolase (up-regulation) and Ribosomal Protein L18a (down-regulated) seem to be regulated in a manner to potentially confer a degree of protection from the sequential infection in BALB/c mice." (PMID 30279404, 2018). "We identified 6 genes found to be common in all three levels of infection whose expression level increases withthe increase in the level of infection (OASL, IFI27, IFIT1, IFIT3, RSAD2, IFI44L)." (PMID 40255307, 2025). "Neutrophil RNA markers of viral infection, IFI27 and RSAD2, were identified from COVID19 cases and the literature to provide a more complete picture of the infection profile." (PMID 41385588, 2025). "Of these genes, 6 (OASL, IFI27, IFIT1, IFIT3, RSAD2and IFI44L) were in protein-protein interaction network and at each stage of infection." (PMID 40255307, 2025). "Blood samples were drawn in RNA preservative (Tempus) and whole blood RNA was analyzed by droplet digital PCR (ddPCR) for RNA transcripts related to neutrophil response to infection by bacterial (DEFA1; ALPL, IL8RB/CXCR2), and viral (IFI27, RSAD2) pathogens." (PMID 41385588, 2025). "According to the previous study, the identified 6 genes were found to be common in all three levels of infection whose expressionlevel increases with the increase in the level of infection (OASL, IFI27, IFIT1, IFIT3, RSAD2 and IFI44L)." (PMID 40322700, 2025). "IFI27, IFI6, and IFI16 expansion were predicted to initiate a median of 0.27, 0.72 and 0.52 days post-infection, respectively." (PMID 39575237, 2024). "Immune response genes such as the pro-inflammatory cytokine CXCL10, IFI27, USP18, IFIT1, and RSAD2/Viperin were shared between both in vivo infection times and A549 cells." (PMID 39065267, 2024). "IFI27 expression was upregulated by 60-and 3-fold at 24 h post-infection (hpi), and by 55 and 40-fold at 48 hpi, after IAV and SARS-CoV-2 infections, respectively, indicating that IFI27 expression is also induced during IAV and SARS-CoV-2 infections." (PMID 37187533, 2023). "To further estimate the frequency of abortive infections we tested a larger cohort of 99 unselected SN-HCW baseline samples, and found that a comparable proportion (9.1%) had IFI27 induction above the prepandemic threshold." (PMID 34758478, 2022). "To explore this relationship among participants in the replicative infection group, we compared MX1 and IFI27 levels with the average expression of a multigene signature (“STAT1 regulated module”) that we had previously derived and validated as a measure of type 1 IFN bioactivity." (PMID 39616162, 2024). "Though IFI27 was induced following infection of A549-ACE2 cells, it was not induced in infected SVC, nor was IER3 induced in any sample." (PMID 36137009, 2022).